TLR2 (toll like receptor 2)
Diseases named in the same sentence as TLR2 in open-access papers (continued):
Sharing a sentence is not in itself a finding about the gene and the disease.
colitis (continued). "The TLR-2-mediated sensing of OMV-associated PSA was shown to ameliorate colitis severity in an experimental TNBS-colitis model, by increased induction of IL-10-producing Tregs, whereas cDC-derived IL-10 was elevated in a human in vitro system upon OMV exposure." (PMID 41028655, 2025). "Further studies reveal that the toll-like receptor 2/4 (TLR2/4)-NF-κB-NOD-like receptor thermal protein domain associated protein 3 (NLRP3) axis exacerbates colitis by inducing macrophage pyroptosis and IL-1β secretion, amplifying intestinal inflammation and barrier dysfunction." (PMID 41030455, 2025). "Meanwhile, LGG cannot protect TLR2‐deficient mice from colitis induced by Citrobacter rodentium." (PMID 38882496, 2024). "Additionally, studies have shown that the knockout and polymorphic loss of function of TLR2 results in a more severe presentation of colitis in animal models and ulcerative colitis patients, respectively." (PMID 34576099, 2021). "Moreover, TLR2 pathways have been reported to be involved in intestinal barrier function as mice lacking TLR2 expression are more susceptible to microbial-induced colitis." (PMID 30443241, 2018). "Interestingly, we observed that TLR1−/− and TLR2−/− mice were more susceptible to DSS-induced colitis than TLR6−/− and wild-type mice." (PMID 28289440, 2017). "In this study, TLR2−/− mice were susceptible to the colitis induced by DSS." (PMID 27563173, 2016). "Moreover, our results also indicate that deficiency of TLR2 contributes to the high susceptibility of mice to DSS-induced colitis." (PMID 27563173, 2016). "Moreover, TLR2-deficient mice were found to be more susceptible to DSS-induced colitis as shown by the increased severity of colitis." (PMID 27563173, 2016). "Furthermore, TLR2 signaling has been reported to play a protective role in an experimental model of colitis-associated colorectal cancer, and polymorphisms of TLR2 have shown to be associated with gastric cancer." (PMID 23760261, 2013). "Next, we examined the impact of TLR2-deficiency on colitis-associated tumor development." (PMID 20885960, 2010). "We provide evidence that colonic epithelium of TLR2−/− mice have altered immune responses and dysregulated proliferation under steady-state conditions and during colitis, which lead to inflammatory growth signals and predisposition to accelerated neoplastic growth." (PMID 20885960, 2010). "Consistent with our proposal, paeonol was reported to alleviate C. albicans-associated colitis induced by DSS in mice through suppressing dectin-1/NF-κB signaling in combination with TLR2 and TLR4, while the antifungal drug fluconazole treatment could rescue the ulcerative colitis symptoms in mice." (PMID 37540386, 2023). "After colitis induction in both mice strains, damage-associated molecular markers were released by the damaged colon tissue bound with the Toll-Like Receptors (mainly Tlr2 and Tlr4) and activated flares of inflammatory responses first-line defense mechanism of hosts." (PMID 35263357, 2022). "Thus, we next determined whether the TLR2 signaling pathway is responsible for B. fragilis protection against development of colitis-associated CRC." (PMID 30429227, 2018). "Moreover, TLR-2-/- mice are more susceptible to DSS- induced colitis." (PMID 25816321, 2015). "Thus, TLR2-deficiency prevented the induction of T-cell-mediated colitis in NOD2−/− mice 36 and a recent study reported that NOD2 may down-regulate multiple TLR responses." (PMID 19950179, 2010). "While A. muciniphila-derived EVs (AmEVs) have shown promise in ameliorating colitis through Toll-like receptor 2 (TLR2) signaling suppression and mucosal repair, their potential to mitigate colitis-associated cognitive deficits remains unexplored." (PMID 41496520, 2026). "Prior studies have demonstrated that HSP65‐producing L. lactis prevents arthritis and colitis in mice dependent on mechanisms such as TLR2 and induction of these regulatory T cells." (PMID 40745935, 2026).
colitis (continued). "TLR2 expression levels were significantly higher in both colitis (p < 0.001) and TA-administered colitis (p < 0.05) mice compared to the normal control group." (PMID 40333150, 2025). "shown via cellular and animal studies that TLR2 downregulation impeded the growth of patients with sporadic CRC and colitis‐associated cancer, indicating a potential role for TLR2 in the development of CRC." (PMID 38685971, 2024). "NOD2-mediated negative regulation of TLR2-mediated Th1 responses, which was initially reported in in vitro studies, was also observed in an in vivo colitis model." (PMID 39403381, 2024). "Probiotic Clostridium butyricum promotes IL‐10 production by CD11b+CD11c(int) intermediate F4/80+ intestinal macrophages via the TLR2/MyD88 signaling pathway in dextran sodium sulfate (DSS)‐induced colitis." (PMID 38604998, 2024). "rTsgal also alleviated DSS-induced murine colitis by inhibiting the TLR-4 (TLR-2)/MyD88/NF-κB signaling pathway, reducing excessive inflammatory responses, improving inflammatory cell infiltration and tissue damage." (PMID 39456703, 2024). "This bacterium has a dose-dependently protective effect on DSS-induced colitis, which is closely related to the down-regulation of IL-17 secretion and inhibition of toll-like receptor 2 (TLR-2)." (PMID 39140035, 2024). "In the colon, Lactobacillus breves DM9218 expressed TLR2, which directly stimulated γδ T cells and had positive effects on colitis." (PMID 39749132, 2024). "Studies have shown that TLR2 is involved in the protection of PSA against colitis and autoimmune encephalomyelitis." (PMID 37740010, 2023). "It has been reported that A. muciniphila secretes the Amuc_1100 protein, which induces the anti-inflammatory cytokine interleukin-10 via toll-like receptor 2 and improved colitis in mice." (PMID 37444313, 2023). "In DSS colitis model, Clostridium butyricum directly triggers TLR2/MyD88-dependent IL-10 production by intestinal macrophages in inflamed mucosa to prevent colitis development, and this prevention can be negated in macrophage-specific IL-10-deficient mice." (PMID 35967333, 2022). "For instance, Clostridium butyricum directly triggered IL-10 production by intestinal macrophages in inflamed mucosa via the TLR2/MyD88 pathway, thereby preventing experimental colitis in mice." (PMID 35241180, 2022). "As a piece of more direct in vivo evidence on the PRR-driven interaction between IMCs and intestinal pathogens, TLR2 expression on tissue-resident cells was found to mediate protection against Citrobacterrodentium (C.rodentium) induced lethal colitis." (PMID 35563571, 2022). "In another study, pretreatment of C57BL/6 mice with Lactobacillus rhamnosus GG (LGG) improved CR-induced colitis in a TLR2-dependent manner." (PMID 36145206, 2022). "In rats with 5-fluorouracil-induced colitis, the TLR2/MyD88/NF-κB pathway is activated to speed up inflammation, whereas patchouli alcohol (PA) slows down colitis through TLR2/MyD88/NF-κB pathway inhibition." (PMID 36555481, 2022). "In the DSS-induced colitis model, the administration of S. boulardii decreased colonisation by C. albicans as well as colonic inflammation in mice, with a reduction in pro-inflammatory cytokine expression and a difference in expression of TLR2." (PMID 35630457, 2022). "Clostridium butyricum, another Clostridium strain, which has been clinically used in regulating intestinal health with the mechanism via activating TLR2/MyD88 signaling pathway in colitis." (PMID 34917080, 2021). "Conversely, exposure of cultured human colorectal cells and mice with induced colitis to various commensal Lactobacillus strains exerts a beneficial influence on intestinal barrier function in a TLR2-dependent manner." (PMID 34814947, 2021).
colitis (continued). "Naturally, the effects of curcumin on the regulation of TLRs signaling pathways in colitis mice were further investigated by Western blot analysis, including TLRs signaling molecules TLR2 and TLR4 and the downstream proteins MyD88, NF-κBp65, p38MAPK, and AP-1." (PMID 34567209, 2021). "Mice deficient for either TLR2, 4, 5, and 9, the TLR-pathway mediator MyD88 or the NLRP6 inflammasome are highly susceptible to experimentally induced colitis." (PMID 33538854, 2021). "NOD2-deficient mice were susceptible to this unique type of colitis due to the excessive production of pro-inflammatory cytokines via TLR2 activation, because the mice deficient in both NOD2 and TLR2 were protected from colitis." (PMID 33935757, 2021). "Focusing on the well-studied TLRs, deficiency of TLR2 is associated with aggravated colitis in DSS-treated mice and multidrug resistance colitis." (PMID 34368179, 2021). "Normal TLR2 activity helps maintain intestinal epithelial structure and function in colitis models, reducing the damage done to the mucosal membrane in DSS-induced colitis." (PMID 34576099, 2021). "Studies with antibiotics suggest that PAMPs released by commensal organisms also activate TLR2/TLR4 in DSS colitis." (PMID 33552081, 2020). "It was further demonstrated that the amelioration of dextran sulfate sodium-induced colitis by EcN is mediated via TLR-2- and TLR-4-dependent pathways." (PMID 33679699, 2020). "This work establishes that the TLR2/1 agonist PAM3 significantly reduces the severity of DSS induced colitis." (PMID 32269253, 2020). "The TLR2/4/MyD88/NF-κB signaling pathway was significantly activated in the DSS-induced colitis group." (PMID 32337275, 2020). "The effect of Hsp65-lac was shown to be dependent on TLR-2 signaling in colitis as it was in our model." (PMID 33072101, 2020). "A study has confirmed that MAL serves as a bridge between TLR2/TLR4- and MyD88-mediated signaling to orchestrate downstream inflammatory responses and regulate intestinal homeostasis and colitis-associated colorectal cancer in mice." (PMID 32099532, 2020). "For example, commensal Bacteroides fragilis polysaccharide promotes TLR2 dependent development of IL-10 producing Tregs and tolerance in experimental colitis." (PMID 30717413, 2019). "Polysaccharide A (PSA) from B. fragilis induces the production of interleukin (IL)-10 from immune cells via Toll-like receptor 2 (TLR2) signaling in animal colitis models." (PMID 30065713, 2018). "More importantly, we found that PSA of B. fragilis inhibited the development of colitis-associated CRC in an azoxymethane (AOM)/DSS-induced animal model and that its beneficial effect against colon tumorigenesis was mainly determined by TLR2 signaling." (PMID 30429227, 2018). "In colitis groups, n-3 diet upregulated IL-1A, TLR-2, and MA2K3 genes while n-9 diet upregulated TLR-4 genes (P = 0.044, P = 0.013, and P = 0.021, resp.)." (PMID 29670469, 2018). "Another group has shown that deletion of TLR2 in the multidrug resistance model of colitis resulted in more aggressive disease." (PMID 29515999, 2018). "A subsequent study by the same group confirmed the essential role of TLR2 in the modulation of colitis by B. fragilis." (PMID 29515999, 2018). "In an animal model of colitis, TLR2−/− mice developed more severe colonic inflammation than wild-type mice." (PMID 28289440, 2017). "Under conditions of injury, however, MyD88-, TLR2-, and TLR4-deficient mice show increased susceptibility to dextran sodium sulfate (DSS)-induced colitis." (PMID 29354132, 2017). "The aim of this study was to determine the impact of TLR1, TLR2, and TLR6 deficiency on inflammatory parameters associated with C. albicans colonization and acute colitis induced by DSS by comparing wild-type, TLR1−/−, TLR2−/−, and TLR6−/− mice." (PMID 28289440, 2017).
colitis (continued). "Upon administration of DSS, mice in the WT/GF/DSS, TLR4/GF/DSS, and TLR2/GF/DSS groups developed severe colitis and colitis-related signs (based on colon lengths and fecal occult tests)." (PMID 28683149, 2017). "Oral administration of LL-LcrV significantly enhanced colonic IL-10 production in a TLR-2-dependent manner and was able to prevent and improve colitis in two different mouse models." (PMID 29387056, 2017). "Oral administration of L. lactis secreting HSP65 is able to completely prevent DSS-induced colitis in an IL-10/TLR-2-dependent manner." (PMID 29387056, 2017). "In order to address the consequences of TLR2 deficiency for intestinal physiology, we employed DSS-induced colitis." (PMID 27563173, 2016). "An unaltered microbiota was required for colitis exacerbation in TLR2/MDR1A double-knockout mice once protection from colitis was observed upon antibiotic treatment." (PMID 26925061, 2016). "After the establishment of experimental colitis, the expressions of TLR2, TLR4, and TLR9 were enhanced in the inflammatory cells which were located in lamina propria and submucosa." (PMID 25276470, 2014). "Several classes of plant natural products have been examined previously in the context of TLR2 signaling, including one study addressing their role in colitis." (PMID 23760261, 2013). "Analysis of mucosal damage score demonstrated that, with the exception of TLR4−/− mice which showed a less severe disease, the severity of the colitis was essentially similar in wild type, TLR2−/−, TLR9−/− and MyD88−/− mice (n = 6; p<0.05)." (PMID 23372731, 2013). "Clearly, although our data suggest dectin-1 signalling is redundant in intestinal inflammation TLR2 and/or TLR6 deficiency does affect experimental colitis via separate mechanisms indicating that dectin-1 deficiency does not seem to affect TLR signalling." (PMID 22507600, 2012). "For example, PAMP-sensing by intestinal epithelial cells has been reported to induce the expression of bactericidal and barrier-enhancing mediators, and deficiency in TLR2, TLR4 or MyD88 was shown to result in increased mortality following DSS-induced colitis." (PMID 20161736, 2010). "This suggests that TLR2-mediated promotion of epithelial repair is largely context dependent, operating at a level of inflammatory stress greater than that induced in our colitis models." (PMID 19950179, 2010). "Previous findings using murine models of exposure to enteric bacterial pathogens and chemically-induced colitis indicated that TLR-2 plays a critical role in the maintenance of mucosal integrity." (PMID 20509914, 2010). "We utilized the AOM-DSS model for colitis-associated colorectal cancer (CAC) in wild type (WT) and TLR2−/− mice." (PMID 20885960, 2010). "Similarly, Bacteroides fragilis attenuates DSS-induced colitis in mice through the TLR-2/IL-10 signal pathway." (PMID 39699251, 2025). "Similarly, Lactobacillus rhamnosus modulated immune cell populations by reducing the Th17/Treg ratio through the JAK-STAT signaling pathway, mediated by toll-like receptor 2 (TLR2) in a DSS-induced colitis mouse model." (PMID 39861184, 2025). "Similarly, NTBF outer membrane vesicles (OMVs), which are rich in PSA, activate TLR2-mediated IL-10 production, enhancing the generation of Tregs to prevent experimental colitis." (PMID 40292216, 2025). "Finally, the administration of RIPK2 siRNA protected NOD1- or NOD2-deficient mice from DSS-induced colitis, suggesting that RIPK2, activated by TLR2 and/or TLR4, plays a colitogenic role." (PMID 39403381, 2024). "In addition, theabrownin from Pu-erh tea improves DSS-induced colitis by restoring gut homeostasis and inhibiting TLR2&4 signaling pathway." (PMID 39272608, 2024). "On the other hand, B. fragilis was shown to be protective against colitis and colitis-induced colorectal cancer by TLR2 signaling via polysaccharide A production, which was also found to be responsible for ameliorating abnormal metabolism of the anti-fungal agent voriconazole." (PMID 39229279, 2024).
colitis (continued). "TLR2 stimulation had a protective effect on tight junctions in animals, explants and primary human intestinal cells in culture, and both Tlr2 and Myd88 knockout mice exhibit an accelerated disruption of the barrier following colitis induction." (PMID 37997696, 2023). "Moreover, TLR2-, TLR5- and TLR9-deficient mice are also more susceptible to chemically induced colitis." (PMID 36982420, 2023). "In addition, studies have shown that L. casei Lbs2 protects from experimental colitis through TLR2-dependent induction of T-regulatory response." (PMID 35241180, 2022). "Studies have shown that TLR2 mRNA expression in intestinal mucosal tissue is significantly higher in IBD patients compared to normal subjects, while TLR1 R80T and TLR2 R735G heterozygous carriers are at increased risk of total colitis." (PMID 35955628, 2022). "Moreover, induced expression of the pro-fibrogenic cytokine IL-11 in αSMA+ myofibroblasts of the muscularismucosae was also part of the TLR2-dependent protection from mucosal damage upon C.rodentium-induced colitis." (PMID 35563571, 2022). "Previous study has shown that cell surface polysaccharides of Bifidobacterium bifidum could activate Toll-like receptor 2 (TLR2)/MyD88 pathway to induce Tregs, displaying robust suppressive capacity toward experimental colitis." (PMID 34217349, 2021). "Exogenous HA acting through TLR2/TLR4 promotes wound repair in DSS colitis." (PMID 33552081, 2020). "Together, these data supported the fact that IG may improve inflammation in DSS-induced colitis through blocking the TLR2/4/MyD88/NF-κB signaling pathway." (PMID 32337275, 2020). "Several studies have proposed that a high expression of TLR-2 and TLR-4 may be associated with IBD pathogenesis, and ultimately can modulate the host’s susceptibility to colitis." (PMID 32872480, 2020). "Deletion of TLR4, TLR2, TLR5 and TLR9 as well as simultaneous deletion of TLR3 and TLR7 led to disturbed epithelial homeostasis and enhanced susceptibility to acute DSS-induced colitis, however with less severe pathology than in MyD88-deficient mice." (PMID 29570694, 2018). "In addition to directly acting agonists, interfering with TLR2 dimerization has been shown to ameliorate DSS colitis through effects on monocyte activation and to improve Pam3CSK4-induced hepatic inflammation." (PMID 29515999, 2018). "lactis would be sufficient to increase Tregs before the colitis induction and whether TLR2 would be involved in such effect." (PMID 28194152, 2017). "In this study, we explored whether the deficiency in TLR1, TLR2 or TLR6 impacts C. albicans colonization and inflammation-associated colonic injury in the dextran sulfate sodium (DSS)-induced colitis in mice." (PMID 28289440, 2017). "Similarly, the colonization of mice with B. fragilis protects against experimental colitis in a TLR2-dependent manner." (PMID 29354132, 2017). "We suggest that BF prevents DSS-colitis via the TLR2/IL-10 signal pathway." (PMID 28683149, 2017). "TLR2 signaling is related to colitis and involved in regulation of innate immunity in the intestinal tract, but the mechanisms remain unclear." (PMID 27563173, 2016). "Similarly, the extracellular polysaccharide A of Bacteroides fragilis, has also been shown to expand the number of mucosal Foxp3+ T cells and confers a TLR2-dependent protection in mouse colitis models." (PMID 25910186, 2015). "Given the potential for RA to promote either regulatory or inflammatory immune responses depending on the status of the tissue microenvironment, we assessed the effects of RA supplementation during acute colitis and evaluated the role of TLR2 in modulating these effects." (PMID 25826367, 2015). "Our previous study has shown that high expressions of TLR2, TLR4, and TLR9 in the colonic mucosa of experimental colitis rats and a positive correlation between intestinal damage degrees, which implied TLR2, TLR4, and TLR9, prompt the immune injury of murine intestinal in experiment colitis." (PMID 25276470, 2014).